GPNMB (glycoprotein nmb)
Diseases named in the same sentence as GPNMB in open-access papers (continued):
Sharing a sentence is not in itself a finding about the gene and the disease.
breast cancer (continued). "GPNMB expression in tumor epithelium was an independent prognostic factor for breast cancer recurrence." (PMID 29799853, 2018). "Elevated expressions of GPNMB/OA have been shown to promote invasion and metastasis of prostate, hepatocellular carcinoma, glioma and breast cancer." (PMID 26883195, 2016). "The glycoprotein nmb (GPNMB), for example, was characterized with high expression in all breast cancer subtypes versus normal tissues in average, but with relatively high expression in some normal tissues (breast, heart, lung and skin)." (PMID 26700623, 2016). "Another report showed that GPNMB/OA is highly and selectively expressed in aggressive bone-metastatic sub-populations of 4T1 breast cancer cells." (PMID 26883195, 2016). "NRP-1 expression is increased by a glycoprotein named transmembrane NMB (GPNMB), which is known to promote malignant phenotype in breast cancer." (PMID 26558271, 2015). "GPNMB/OA promotes the migration, invasion and metastasis of breast cancer cells; it is commonly expressed in basal/triple-negative breast tumors and is associated with shorter recurrence-free and overall survival times in patients with breast cancer." (PMID 20711474, 2010). "GPNMB/OA is constitutively shed from breast cancer cells in an ADAM10-dependent manner and the shed GPNMB/OA ECD is capable of inducing endothelial cell migration in vitro." (PMID 20711474, 2010). "Given that we employed a syngeneic mouse breast cancer model to initiate our studies, we examined this possibility and found that GPNMB/OA expression was able to promote the growth of 66cl4 cells in both an immunocompetent and immunocompromised background." (PMID 20711474, 2010). "Recent studies demonstrating that GPNMB/OA can undergo proteolytic processing led us to investigate the possibility that this protein was subject to ectodomain shedding in breast cancer cells." (PMID 20711474, 2010). "GPNMB/OA increased the incidence of mammary tumor formation and also accelerated tumor outgrowth relative to VC tumors." (PMID 20711474, 2010). "Using immunoblot and ELISA assays, we demonstrate the GPNMB/OA ectodomain is shed from the surface of breast cancer cells." (PMID 20711474, 2010). "Together, these data indicate that ADAM10 is able to release the GPNMB/OA ectodomain from the surface of breast cancer cells." (PMID 20711474, 2010). "We have previously demonstrated that GPNMB/OA expression is elevated during the formation of primary mammary tumors; its expression is further elevated in breast cancer bone metastases and plays a functional role in this process." (PMID 20711474, 2010). "Our data suggests that GPNMB/OA, when expressed in breast cancer cells, can increase vascular recruitment and enhance tumor growth." (PMID 20711474, 2010). "Recently, we demonstrated that GPNMB/OA is highly expressed in several aggressively bone-metastatic sub-populations of the 4T1 mouse mammary carcinoma cell line." (PMID 20711474, 2010). "We have observed that in certain cell-based models, such as 66cl4 mouse mammary carcinoma cells, GPNMB/OA expression can enhance tumor growth in vivo." (PMID 20711474, 2010). "The observation that primary human breast tumors with high MVD express elevated levels of GPNMB/OA in the tumor epithelium provides a clinical correlate that substantiates our in vivo studies with the 66cl4 mammary carcinoma model." (PMID 20711474, 2010). "Previously we have reported that GPNMB/OA expression is increased in in vivo selected aggressively bone metastatic subpopulations of 4T1 mammary carcinoma cells." (PMID 20711474, 2010). "Gene expression analysis showed that GPNMB+ cells significantly upregulated genes involved in invasion and/or tissue remodeling, including EGFR, a direct interactor of GPNMB in breast cancer cells, its downstream targets (STAT3, MMP 2-3-9) and ITGB4, TGFβ, VEGF and VCAM." (PMID 40528051, 2025).
breast cancer (continued). "Furthermore, single-cell profiling of myeloid cells from patients with breast cancer identified lipid-associated macrophages that co-expressed the TTR macrophage markers CD63, LIPA, GPNMB, MCR1, CD163, and MSR1." (PMID 38942020, 2024). "Furthermore, the antibody-drug conjugate glembatumumab vedotin (GV), which specifically targets GPNMB, has shown initial efficacy in clinical trials for breast cancer, metastatic uveal melanoma, and osteosarcoma 18-20." (PMID 38706915, 2024). "GPNMB was found to be highly expressed in breast cancer samples." (PMID 35986230, 2022). "GPNMB cleavage by ADAM10 was previously demonstrated in breast cancer cells." (PMID 35280996, 2022). "As reported in breast cancer, GPNMB-positive cells might have CSC characteristics and the ability to induce EMT." (PMID 36061142, 2022). "GPNMB overexpression in metastatic mouse mammary tumor cells could upregulate tumor growth, stimulate bone metastasis and induce EMT15." (PMID 34108545, 2021). "Overall, these results implicated GPNMB overexpression is a biomarker of poor prognosis in TNBC and may lead to breast cancer recurrence with distant metastasis." (PMID 34108545, 2021). "These outcomes were in consistence with our in-house data analysis which showed GPNMB mRNA overexpression in TNBC may promote breast cancer recurrence especially in terms of distant metastasis." (PMID 34108545, 2021). "Transmembrane glycoprotein NMB (GPNMB) was detected in stage 3 breast cancer tissues." (PMID 31945087, 2020). "Glembatumumab vedotin (GV) is an antibody–drug conjugate consisting of a gpNMB-specific monoclonal antibody coupled to the microtubule inhibitor monomethyl auristatin E (MMAE) that has shown effect in the treatment of gpNMB-expressing breast cancer." (PMID 32961800, 2020). "Functionally, GPNMB can promote cell migration, invasion and metastasis in breast cancer cells." (PMID 29799853, 2018). "Additionally, GPNMB expression was most abundant in triple negative breast cancer and was a prognostic marker for shorter metastasis-free survival times within this breast cancer subtype." (PMID 29799853, 2018). "GPNMB has been shown to induce aggressive cellular phenotypes in breast cancer and has been identified as a potential therapeutic target for patients with basal-like breast cancer (BLBC) and TNBC46,47." (PMID 30568280, 2018). "In this case, GPNMB is a prognostic biomarker, however, to date there a no reports that it has a causal role in breast cancer." (PMID 29799853, 2018). "In human breast cancer, there is still a debate between different studies whether GPNMB acts as a tumor suppressor or an oncogene." (PMID 30400781, 2018). "This is particularly important since earlier studies on other types of cancers (hepatocellular carcinoma, glioma and breast cancer) have shown that GPNMB/OA is expressed at higher levels in several malignant human tissues relative to corresponding normal tissues." (PMID 26883195, 2016). "The possibility that GPNMB/OA ECD protein-integrin interaction contributed to lung cancer growth was also demonstrated in a recent report that GPNMB/OA cooperates with neutropilin-1 to promote mammary tumor growth and engages integrin α5β1 for efficient breast cancer metastasis." (PMID 26883195, 2016). "Thus, GPNMB/OA represents an attractive target for therapeutic intervention in breast cancer; however, little is known about the functions of GPNMB/OA within the primary tumor microenvironment." (PMID 20711474, 2010). "Whether GPNMB/OA-expressing mammary tumors are characterized by increased numbers of infiltrating TAMs requires further investigation." (PMID 20711474, 2010). "Having determined that GPNMB/OA is constitutively shed in an ADAM10-dependent manner in our breast cancer model systems, we next investigated whether this shed GPNMB/OA ECD possessed angiogenic properties." (PMID 20711474, 2010).
breast cancer (continued). "To assess whether a similar mechanism could account for GPNMB/OA-induced mammary tumor growth observed in Balb/c mice, we performed a second set of mammary fat pad injections into athymic mice that lack functional T-cells." (PMID 20711474, 2010). "Moreover, we showed that ectopic expression of GPNMB/OA in poorly metastatic 66cl4 mouse mammary carcinoma cells is sufficient to induce MMP-3 expression and increases their invasion in vitro and promotes bone metastasis in vivo." (PMID 20711474, 2010). "GPNMB has demonstrated significant expression in malignant tissues and has been recognized as a promising therapeutic target in various types of cancer, including epithelial ovarian cancer, hepatocellular cancer, colorectal cancer, breast cancer, and NSCLC 12-17." (PMID 38706915, 2024). "Meanwhile, some researchers have reported that GPNMB is overexpressed and secreted by breast cancer cells, contributing to breast cancer cell survival, which indicates that downexpression of GPNMB could be considered as a prospective target for treating tumors." (PMID 37786733, 2022). "Glycoprotein nonmetastatic melanoma protein B (GPNMB) has received significant attention in breast cancer treatment, in which it has been associated with cancer stem cells (CSCs) and epithelial-mesenchymal transition (EMT); however, the function of GPNMB in HNSCC is completely unknown." (PMID 36061142, 2022). "For instance, GPNMB overexpresses in a breast cancer cell line that could aggressively metastasize to bone, and SPP1's expression level (also called Osteopontin) is elevated in a variety of metastatic cancers, including colon cancer, hepatocellular carcinoma, and gastric cancer." (PMID 22078224, 2011). "Thus, ectodomain shedding may serve as a novel mechanism by which GPNMB/OA promotes angiogenesis in breast cancer." (PMID 20711474, 2010). "GPNMB, also known as osteoactivin, promotes tumor growth, migration, invasion, and CSC formation in breast cancer." (PMID 36737605, 2023). "The present study identified four genes (AP2B1, APP, GPNMB and DLST) that were significantly downregulated by luteolin in breast cancer cell lines." (PMID 35678671, 2022). "GPNMB-positive cells in breast cancer also show an increased expression of EMT-related genes such as SNAIL, SLUG, and ZEB1, consistent with the fact that GPNMB-positive cells in HNSCC have shown increased invasiveness and migration." (PMID 36061142, 2022). "The human protein atlas database also found that AP2B1, APP, GPNMB and DLST were highly expressed in breast cancer and that AP2B1 (cut-off value, 75%) was significantly associated with survival rate (p = 0.044)." (PMID 35678671, 2022). "The data suggested that the four genes, AP2B1, APP, GPNMB and DLST, were highly expressed in breast cancer and that AP2B1 was a suitable prognostic marker for breast cancer." (PMID 35678671, 2022). "Upon EZH2 knockdown, fold change in the target gene expression for GPNMB, CoL5A1, POMT2, PMEPA1, VGLL4 and SUMF1 was found to be 1.3, 2.8, 2.2, 2, 1.7 and 1.8, respectively in MCF-7 breast carcinoma cells as detected by qPCR." (PMID 30760814, 2019). "Glycoprotein nonmetastatic melanoma protein B (GPNMB) is a transmembrane glycoprotein found to be highly expressed in many types of cancer, including breast cancer, with various roles in tumour invasion, angiogenesis, cell adhesion and immunosuppression." (PMID 38920683, 2024). "Meanwhile, this research showed that CAF improves the invasion of breast cancer cells via inducing the expression of glycoprotein non-metastatic B (GPNMB) on cancer cells in the 3D microenvironment." (PMID 36159996, 2022). "Glycoprotein nonmetastatic melanoma protein B (GPNMB) was originally identified as a membrane protein, but it has been demonstrated that soluble GPNMB is released from astrocytes, melanocytes, and breast cancer cells." (PMID 33466390, 2021).
breast cancer (continued). "Apart from 98 patients with TNBC, we analyzed total 759 patients with primary breast cancer and showed GPNMB overexpression had no prognostic effect in RFS (P = 0.118), LRFS (P = 0.432) and DMFS (P = 0.182) but OS (P = 0.016)." (PMID 34108545, 2021). "It corresponded with our previous results that GPNMB correlated with worse outcome in TNBC subtype but not in all breast cancer subtypes." (PMID 34108545, 2021). "Thus, GPNMB and NRP-1 must have an important role in mammary tumor growth and metastasis mediated by α5β1 integrin." (PMID 26558271, 2015). "We ectopically expressed GPNMB/OA in BT549 cells, a basal breast cancer model." (PMID 20711474, 2010). "Glycoprotein non-metastatic melanoma protein B (GPNMB)/Osteoactivin (OA) is a transmembrane protein expressed in approximately 40–75% of breast cancers." (PMID 20711474, 2010). "In our study, we specifically investigated whether ADAM10 and ADAM17 were responsible for constitutive shedding of GPNMB/OA in breast cancer cells, thus it is possible that ADAM17 is also capable of shedding GPNMB/OA in the context of PMA stimulation." (PMID 20711474, 2010). "In addition, the HPA database demonstrated that AP2B1, APP, GPNMB and DLST were highly expressed in breast cancer; the increased expression of AP2B1 (cut-off value, 75%) was significantly associated with the survival rate (p = 0.044) of 1075 patients with breast cancer." (PMID 35678671, 2022). "However, the transcription factor that is responsible for the GPNMB expression in glioblastoma and breast cancer has not been investigated." (PMID 21209915, 2010). "Moreover, epithelial, but not stromal, GPNMB/OA expression is a prognostic indicator of cancer recurrence across all breast cancer subtypes, and specifically within “triple negative” breast cancers." (PMID 20711474, 2010). "GPNMB drives an increase in NRP1 levels, which in turn potentiates VEGF signaling in breast cancer cells to mediate the growth but not metastasis of these cells in an in vivo experimental model." (PMID 37894289, 2023).
Parkinson disease (42 papers, 2016 to 2026). A progressive degenerative disorder of the central nervous system characterized by loss of dopamine producing neurons in the substantia nigra and the presence of Lewy bodies in the substantia nigra and locus coeruleus. "Genome-wide association studies have identified Glycoprotein Nmb (GPNMB) as a risk factor for Parkinson's disease." (PMID 41406229, 2025). "We show that GPNMB is secreted in response to lysosomal stress via lysosomal exocytosis and highlight the Parkinson's disease risk factor LRRK2 as a strong modulator of GPNMB secretion." (PMID 41406229, 2025). "Research also determined the positive association between serum levels of GPNMB and disease presence and severity of Parkinson’s Disease." (PMID 36875463, 2023). "Previous MR studies on Alzheimer’s disease suggest potential causal associations with BIN1, CCL27, C3, CD33, CD4 T cells, GDF-15 and SVEP1, whereas MR studies on Parkinson’s disease suggest a potential causal association with GPNMB, IL-6 and MIP1b." (PMID 37118290, 2022). "Through downstream analysis, we highlight disease-relevant, translatable pQTLs by presenting new evidence supporting protein-disease associations; most notably, CD33 and Alzheimer’s disease, GPNMB and Parkinson’s disease, and MSR1 and schizophrenia." (PMID 34857772, 2021). "The association of GPNMB with disease resolution is corroborated by the studies that associate GPNMB mutations with a predisposition to Parkinson’s Disease and Autosomal-Recessive Amyloidosis Cutis Dyschromica." (PMID 34054862, 2021). "GPNMB is also elevated in the substantia nigra of patients with Parkinson's disease, a neurodegenerative disease increasingly linked to lysosome dysfcuntion." (PMID 33028409, 2020). "Intriguingly, variants in GPNMB are associated with Parkinson’s disease, highlighting the potential importance of GPNMB broadly in neurodegenerative diseases." (PMID 33028409, 2020). "Our finding suggests that lifestyle changes, particularly a reduction in alcohol consumption for carriers of the rs199347 GG genotype, could modulate GPNMB expression, thereby identifying a potentially modifiable risk factor in Parkinson’s disease." (PMID 39091454, 2024). "GPNMB has been implicated in many cellular processes including proliferation, cell adhesion and inflammation and shows increased expression in several microglial reactive states including in Alzheimer’s disease, Parkinson’s disease and diabetic retinopathy." (PMID 39593143, 2024). "GPNMB is highly expressed in glia, and is linked with risk for Parkinson's disease." (PMID 37051703, 2023). "Besides, genome-wide association studies demonstrated that GPNMB should be considered as possible Parkinson’s disease-related genes for future studies." (PMID 33726823, 2021). "The International Parkinson’s Disease Genetics Consortium (IPDGC) found that SNP rs156429 in the 7p15 chromosomal region led to decreased risk of developing PD along with increased methylation of CpG sites proximal to the GPNMB gene." (PMID 29519253, 2018). "Therefore, further studies are needed to explore how genetic differences between populations might influence the relationship between the GPNMB rs199347 variant, alcohol consumption, and Parkinson’s disease risk." (PMID 39091454, 2024). "Furthermore, a variant in GPNMB has been linked to Parkinson’s disease." (PMID 39593143, 2024). "The neuroprotective role of GPNMB has been observed in amyotrophic lateral sclerosis and Parkinson’s disease." (PMID 40653468, 2025). "As expected however plasma gpNMB concentrations among patients with Parkinsonism were higher in those with type 1 Gaucher disease than either GBA1 heterozygotes or those with idiopathic PD (p=0.0001)." (PMID 41152894, 2025). "GPNMB is expressed by activated microglia and is involved in phagocytosis of pathological material; elevated GPNMB levels correlate with disease severity in Parkinson’s disease and lysosomal dysfunction in neurodegeneration." (PMID 41515962, 2025).